EPO (erythropoietin)
Diseases named in the same sentence as EPO in open-access papers (continued):
Sharing a sentence is not in itself a finding about the gene and the disease.
infection (continued). "In addition, GCSF and EPO levels increased in mice that received either 20 or 60 mg/kg b.w. of PHZ upon infection." (PMID 40590713, 2025). "Recent studies have shown that combining IST with androgens, granulocyte colony-stimulating factor (G-CSF), erythropoietin (EPO), or IL-11 can reduce early mortality, infection risk, and bone marrow suppression in patients with SAA, offering a treatment option for those with impaired organ function." (PMID 40926984, 2025). "This could be due to the fact that infection can depress bone marrow, erythropoietin synthesis, decrease intestinal iron absorption, and decrease release from body iron stores and transport." (PMID 39736969, 2024). "Higher levels of circulating EPO were observed in response to (re)infection." (PMID 38892340, 2024). "However, although not statistically significant, treatment with DMOG increased basal EPO levels in the lung, which appeared to be sustained with infection (p = 0.07)." (PMID 37417946, 2023). "Interestingly, shRNA-mediated Fanca downregulation in EPO-dependent TgSpi1FA+/+ cell lines (#138, #445, #479) was unable to confer EPO independence in vitro 9 days post-infection." (PMID 37573408, 2023). "During inflammation and infection, proinflammatory cytokines may affect erythrocyte maturation by interfering with erythropoietin, which leads to an increase in RDW." (PMID 35505395, 2022). "Furthermore, there was a significant increase in erythropoietin (EPO) in the lung on day 4 after infection." (PMID 35076028, 2022). "Furthermore, myeloid EPOR deficiency resulted in a prolonged Ri (approximately 20 hrs in the EPOR-cKO mice and approximately 16 hrs in the control mice), indicating the important role of macrophage EPO signaling in promoting infection resolution." (PMID 33927725, 2021). "Collectively, macrophage EPO signaling is temporally induced during infections." (PMID 33927725, 2021). "In this self-limited infection model, the EPO concentration in the peritoneal fluid at all observed time points (4, 12, 24, 48, and 72 hrs) was significantly higher than at baseline and peaked 4 and 12 hrs following infection." (PMID 33927725, 2021). "Moreover, EPO ameliorated inflammation and increased the actions of ciprofloxacin and vancomycin in resolution-delayed E. coli- and S. aureus-initiated infections." (PMID 33927725, 2021). "We next sought to investigate the effects of EPO on the delayed resolution of infection." (PMID 33927725, 2021). "Another factor which is likely to impair the erythropoietic response is injury or infection, because the EPO rise may be limited by inflammatory cytokines." (PMID 29695978, 2018). "In view of the ambiguous results of previous studies, regulation of EPO production by inflammatory cytokines and the relationship of injury and infection with the response to hypoxia remain unclear and require further research." (PMID 29695978, 2018). "After infection with Aspergillus fumigatus, neutropenic mice were randomized to receive vehicle or 7.5 mg/kg liposomal amphotericin B (LAmB) or 7.5 mg/kg LAmB combined with 1000 IU/kg EPO (16 mice per group)." (PMID 25352847, 2014). "In order to investigate whether EPO is involved in nematode-induced lung dysfunction during primary or challenge infection, lung function was measured by whole body plethysmography at 5, 10 and 20 days following challenge." (PMID 24626328, 2014). "Interestingly, when EPO was combined to LAmB, the percentage of disseminated infection was reduced from 33% in LAmB treated mice compared to 0% in LAmB/EPO treated mice." (PMID 25352847, 2014). "The anti-EPO antibody levels were measured, at infection and at recovery." (PMID 23978045, 2013). "However, when EPO levels at infection was compared in all the mice strains, EPO levels in NZW was significantly higher than Balb/c (p < 0.05)." (PMID 23978045, 2013).
infection (continued). "The lower rates of infection in our study might be due to decreased transfusion requirements owing to the availability of erythropoietin and better screening of blood and blood products for blood-borne infections." (PMID 23533739, 2013). "The means of anti-EPO Ab levels at infection and recovery differed (p = 0.0008)." (PMID 23978045, 2013). "Interestingly, cerebral EPO mRNA expression is induced during the course of infection, while EPOR mRNA declines." (PMID 22094132, 2012). "Thus, the specific modulation of extra-erythropoietic EPO activity forms an attractive therapeutic target in infection and inflammation." (PMID 22094132, 2012). "It is also possible that alterations in normal kidney function due to infection may reduce the production of erythropoietin, thereby curtailing RBC production and masking hemoconcentration." (PMID 20846417, 2010). "Since the peak percentage of parasitaemia occurred earlier in CB than in AS infections it might be that an impaired response to EPO by erythroid progenitor cells is detectable at an earlier time point in CB-infected animals." (PMID 18439291, 2008). "Second, we did not look at several parameters known to influence Hb level and EPO dose, such as residual renal function, adequacy parameters, inflammation/infection, nutritional parameters, treatment with ACE inhibitors, angiotensin II receptor antagonists and level of iPTH." (PMID 19077225, 2008). "However, the weekly average EPO dose remained higher than the pre-infection dose." (PMID 38649863, 2024). "Our results reveal a so far undescribed inflammatory EPO-dependent pathway of DC differentiation and establish a mechanistic link between innate immune recognition of potential immunosuppressive pathogens and the maintenance of the DC pool during and after infection." (PMID 32849551, 2020). "To determine whether this inadequate erythropoietic response was due to a deficiency in erythropoietin (EPO), we quantified plasma EPO levels and found that levels were significantly higher in rhesus macaques compared to cynomolgus macaques during infection (p = 0.007)." (PMID 31831787, 2019). "In contrast to this hypothesis, EPO levels were significantly increased during acute infection." (PMID 28938907, 2017). "The gain in CFU-GEMM might be caused by an advantageous transduction ability of multipotent progenitor cells, whereas the gain in megakaryocyte vs. erythroid component, as indicated by increased BFU-Mk/E colonies, might be related to the Erythropoietin deprivation during the infection procedure." (PMID 25474253, 2014). "EPO can induce the expansion of CD45+ CECs, while EPO neutralization prevents infection-related CEC accumulation." (PMID 39474425, 2024). "While EPO was downregulated, GLUT1 and LDHA expression was significantly induced upon infection especially at 24 h post infection." (PMID 36611805, 2022). "We first detected the temporal expression of EPO and EPOR in a self-limited infection model induced by intraperitoneal administration of E. coli (105 c.f.u. per mouse)." (PMID 33927725, 2021). "In VeroE6 cells, SARS-CoV-2 negatively affected DDC, ACE2, dACE2 and EPO mRNA levels, and induced cell death, while ISG56 was enhanced at early hours post-infection." (PMID 34185793, 2021). "Herein, we found that erythropoietin (EPO) promoted the resolution and enhanced antibiotic actions in Escherichia coli (E. coli)- and Staphylococcus aureus (S. aureus)-initiated infections." (PMID 33927725, 2021). "Moreover, we report that the combination of EPO with antibiotics further increases the clearance of bacteria and improves the outcomes of infections, suggesting that EPO may represent a potential adjunctive therapy with antibiotics for the treatment of certain bacterial infections." (PMID 33927725, 2021).
infection (continued). "Moreover, we report that the combination of EPO with antibiotics further increases the clearance of bacteria and improves the outcomes of infections, suggesting that combinational therapy with antibiotics and EPO may achieve a synergistic maximal benefit for treating infections." (PMID 33927725, 2021). "Collectively, these observations suggest that EPO-induced macrophage CD36 enhances E. coli phagocytosis and promotes infection resolution." (PMID 33927725, 2021). "Anti-EPO antibody was significantly different in the mice strains (mean OD450nm values: Balb/c (2.1); B6 (1.3); CBA (1.4); NZW (1.7)) at infection (p = 0.045)." (PMID 23978045, 2013). "While the strong and consistent association between TfR and EPO is striking, particularly when compared to the lack of association between TfR and ferritin, it was not surprising that ferritin did not explain much of the variability in TfR given its association with infection and inflammation." (PMID 16390553, 2006). "In addition, the blood transfusion process may be accompanied by the use of some drugs or interventions to reduce blood loss, RBC requirements and infection rates, such as perioperative iron and erythropoietin supplementation, which our article did not consider." (PMID 40410779, 2025). "Consistent with a pro-inflammatory state, LPS-preconditioning significantly increased EPO, IFN-γ, IL-1β, KC, TNF-α, MCP-1, MIP-1α, and IFN-β levels in the lungs and pulmonary FTT infection significantly reduced IFN-γ, IFN-β, and MMP9 levels among LPS preconditioned mice." (PMID 37883420, 2023). "Infection resulted in significantly elevated EPO expression at 8 dpi in Cish+/+ mice, but not in the Cish−/− mice from a similar basal level." (PMID 38029163, 2023). "In this study, we found that EPO was induced following infection and promoted noninflammatory bacterial clearance." (PMID 33927725, 2021). "Considering the central role of bacterial clearance in infection resolution and the restricted localization of EPOR in macrophages, we evaluated whether EPO influences macrophage containment of E. coli in vitro." (PMID 33927725, 2021). "Collectively, these results indicate that macrophage EPO signaling enhances noninflammatory E. coli clearance through PPARγ to promote infection resolution." (PMID 33927725, 2021). "In contrast to EPO and G-CSF which are hematopoietic cytokines, SAA1 is an acute phase protein, primarily produced by the liver, and elevated in the plasma following trauma, infection, inflammatory reactions, and cancer." (PMID 30778109, 2019). "Treatment-related exposures included thalidomide derivatives (IMIDs), proteasome inhibitors, cytotoxic chemotherapy, steroids, erythropoietin-stimulating agents (ESAs), stem cell transplants (SCT), hospitalizations, infection, and central venous catheters (CVC)." (PMID 27999418, 2016). "As expected, the predominant population of the cells expanded in StemCell media (without EPO) was negative for VP1u receptor expression (94.1% negative) and further indicated low B19V internalization signal and no significant infection." (PMID 27690083, 2016). "In the present study, we found increased PGE2 concentration in Hc-infected mice, but EPO treatment before the infection reduced PGE2 concentration, although no reduction in mortality was associated with this phenomenon." (PMID 26538835, 2015). "We found that the serum erythropoietin concentration was increased in response to infection with PyNL in GKO mice similarly to that in WT mice (data not shown)." (PMID 26136736, 2015). "The nonerythroid effects of EPO have been described such as their role in immune system activation for controlling some infections." (PMID 26538835, 2015). "The effect of EPO pretreatment on the cell populations in the bronchoalveolar space with or without infection was investigated." (PMID 26538835, 2015).
infection (continued). "Infection with Salmonella was reported to significantly elevate systemic EPO concentration, without substantially altering the proportions of Ter119+ erythroid cells in peripheral blood." (PMID 26068006, 2015). "Whole body plethysmography indicated that nematode-induced changes in airway physiology were reduced in challenge infection in the absence of eosinophils and also during primary infection in the absence of EPO alone." (PMID 24626328, 2014). "While Balb/c anti-EPO Ab levels at infection differed from B6 (p < 0.05), the others were not significantly different when paired." (PMID 23978045, 2013). "Two patients in the EPO group and 6 in the control group showed nonunion (P = 0.02).We detected 1 case of infection in the control group." (PMID 24350133, 2013). "Clarified supernatants from cells infected with the lentiviral EPO vector at an MOI of 1 or 10, and supernatants from uninfected control cells, were likewise used in proliferation assays after 6 days (293H), or 3 and 6 days (CRFK and PBMC) post-infection." (PMID 23028782, 2012). "However, administration of rhEPO to the EPOR-cKO mice following infection did not result in a significant decrease in the Ri, indicating the central role of macrophage EPO signaling to infection resolution." (PMID 33927725, 2021). "In summary, we have found that inflammation induced EPO-dependent TER119+CD11a+ cells that could differentiate into TER119+ and TER119− DC contributing to the replenishment of the DC pool in the spleen and draining lymph nodes after infection." (PMID 32849551, 2020). "Interestingly, the set of data [EPO + hemopexin + total heme] correlated significantly to [TNF-α + IL-10 + IP-10 + MCP-1] during infection, and more specifically for the CM, and NCM groups, but not for MM patients." (PMID 27441662, 2016). "Interestingly absence of EPO also appeared to alter the breathing rate of mice during primary infection." (PMID 24626328, 2014). "Thus, although eosinophils are required for clearance of primary Mf infection, the mechanism of killing is not dependent upon degranulation of EPO." (PMID 24626328, 2014). "To investigate whether eosinophils are involved in both protection and pathology during filarial nematode infection, we explored the role of eosinophils and their granule proteins, eosinophil peroxidase (EPO) and major basic protein-1 (MBP-1), during infection with Brugia malayi microfilariae." (PMID 24626328, 2014). "EPO was not necessary for clearance of Mf in either a primary or a challenge infection." (PMID 24626328, 2014). "Renal cells responsible for erythropoietin production may be injured by the infection and hence the combined effect of haemolysis plus lack of erythropoietin-induced RBC replenishment leads to aggravated reduction in RBC numbers." (PMID 25153636, 2014). "Whether or not EPO affects immune response pathways and the course of disease in infections with viruses, extracellular bacteria or fungi is currently largely unknown." (PMID 22094132, 2012). "The expression levels of EPO and reticulocyte count were not significantly different between the α-TTP knockout and wild type mice before infection." (PMID 30586912, 2018). "Taken together, our data indicate that EPO-dependent inflammatory myeloid cells in spleen and lymph nodes that are transiently marked by TER119 expression contribute to the replenishment of the DC pool in response to an infection." (PMID 32849551, 2020). "Using mice that specifically lack eosinophils or the eosinophil granule proteins, EPO and MBP-1, we definitively confirm and extend our previous results that eosinophils are needed for protection against primary, but not challenge infection of B. malayi Mf." (PMID 24626328, 2014).
infection (continued). "As a result, ex vivo expansion of CD34+ cells in StemCell media without EPO generates a culture with a predominant population of bipotent megakaryocyte-erythrocyte BFU-E progenitors, which in average only allows a very low B19V entry and basically no infection." (PMID 27690083, 2016).
kidney disease (103 papers, 2008 to 2026). "EPO production by organoids would therefore be insufficient to compensate for the loss of EPO-production capacity in kidney disease." (PMID 40221815, 2025). "The increase in blood pressure by EPO can be especially harmful to patients with underlying cardiovascular or kidney diseases." (PMID 38029231, 2023). "This stems from erythropoietin deficiency in the setting of renal disease and bone marrow infiltration." (PMID 36072215, 2022). "In an attempt to address the complications associated with kidney diseases, hiPSC-derived erythropoietin (EPO)-producing cells were successfully generated to discover drugs and develop cell therapy for renal anemia." (PMID 33656639, 2021). "These pathways are altered in kidney disease and are linked to the production of vascular endothelial growth factor, erythropoietin, adiponectin, interleukin (IL)-18, IL-23, and chemokines that bind CXCR3, CXCR4, and/or CXCR7." (PMID 33676416, 2021). "Erythropoietin (EPO): Renal anemia is a condition of kidney disease due to the deficiency of EPO." (PMID 34576149, 2021). "This narrative review summarizes current knowledge on the immunomodulatory properties of vitamin D and EPO, their mechanisms of action on immune cells, and their relevance in kidney disease and transplantation." (PMID 42111895, 2026). "In the clinic pharmacological inhibition of PHD activity is used to overcome insufficient EPO production, most commonly seen in situations of renal disease." (PMID 40853869, 2025). "Interventional studies have shown that zinc supplementation improves the response to erythropoietin therapy in dialysis patients, and beneficial effects of zinc supplementation have been observed in children and adolescents with kidney disease." (PMID 38674257, 2024). "In renal disease, DNA relating to EPO becomes methylated, meaning that HIF cannot bind and promotes a decrease in EPO production." (PMID 39911241, 2024). "It is likely that the changes in the miRNAs’ profile and the increased EPO concentration contributed to the decreased levels of apoptosis in the proximal tubular epithelial cells, and improved renal function in kidney diseases." (PMID 36139786, 2022). "On the other hand, erythropoietin treatment in anemic patients with kidney disease significantly alters the HbA1c levels." (PMID 34277660, 2021). "In supporting the relationship between CAN and kidney disease, the former has been shown to affect the glomerular filtration pressure, glomerular endothelial cell damage and erythropoietin secretion." (PMID 31708736, 2019). "Since prior studies and the present one have shown an impaired EPO response to decreasing hemoglobin levels in renal disease, we excluded subjects with an impaired renal function from our reference subset." (PMID 25915923, 2015). "Extra-renal EPO production has been also described in the liver, although its contribution to the circulating EPO concentration in adults is highly debatable, even in kidney disease states." (PMID 25867633, 2015). "As a result, the bone marrow makes fewer RBCs and therefore patients with kidney disease often have to take erythropoietin supplements." (PMID 21635189, 2011). "In patients who have kidney disease it is likely that production of erythropoietin, the hormone responsible for inducing RBC production, is depressed." (PMID 21635189, 2011). "In normal status, EPO synthesis is transcriptionally regulated by the oxygen level of the body; while in patients with various advanced kidney diseases, the EPO synthesis process can be largely disrupted, which therefore requires supplement with recombinant analogues." (PMID 41179707, 2025). "Considering the prevalence of kidney disease among LPI patients, we hypothesized that Slc7a7 deficiency might lead to kidney dysfunction, resulting in diminished erythropoietin levels and impaired RBC maturation." (PMID 39881295, 2025).